IL16 (interleukin 16)
Diseases named in the same sentence as IL16 in open-access papers (continued):
Sharing a sentence is not in itself a finding about the gene and the disease.
endometriosis (11 papers, 2020 to 2025). The growth of functional endometrial tissue in anatomic sites outside the uterine body. "The rs4778889 polymorphism in the IL16 gene promoter region was found to be significantly associated with the risk of endometriosis in the Nigerian population." (PMID 39767772, 2024). "In gynecology, IL-16 is implicated in endometriosis, ovarian physiology, and ovarian and cervical carcinogenesis." (PMID 39408600, 2024). "Our results revealed that elevated serum concentration of IL-16 was associated with pain severity and genetic polymorphism of IL-16 rs4778889 was associated with endometriosis in Nigerian women." (PMID 37170270, 2023). "Contrary to our findings, Greek and Iranian women with G allele of rs11556218 of IL-16 gene had increased risk of endometriosis." (PMID 37170270, 2023). "• The minor allele ‘C’ of IL-16 (rs4778889) is associated with endometriosis in Nigerian women with endometriosis." (PMID 37170270, 2023). "This explains the exploration of association between serum IL-6 and IL-16 concentration, and IL-6 and IL-16 gene polymorphisms in women with endometriosis in this study to guide further understanding on the pathogenesis of the disease and its symptoms." (PMID 37170270, 2023). "• There is an association between serum concentration of IL-16 and pain severity in women with endometriosis." (PMID 37170270, 2023). "The IL-16 rs11556218 SNP corresponds to a missense mutation wherein asparagine (Asn) is substituted by lysine (Lys) and allele ‘G’ is associated with an increased susceptibility of developing both endometriosis and SLE." (PMID 40725086, 2025). "Additionally, differences in the IL-16 gene have been associated with differing pain levels among people with endometriosis." (PMID 40508188, 2025). "The study demonstrated that individuals with the C allele of rs4778889 exhibited increased susceptibility to endometriosis, potentially due to its role in altering IL-16 expression levels and contributing to the inflammatory environment characteristic of the disease." (PMID 39767772, 2024). "The observed serum IL-16 concentrations were similar across the three polymorphisms investigated in IL-16 gene (rs4778889, rs11556218, and rs4072111) in both the reference group and women with endometriosis (p > 0.05)." (PMID 37170270, 2023). "IL-16 plays a key role in inflammation, and pain is a hallmark of inflammation, and this may explain the association observed between serum IL-16 and severity of pain in women with endometriosis." (PMID 37170270, 2023). "Casp-3 activation and IL-16 cleavage is not necessarily associated with the induction of apoptosis, but recently release of IL-16 has been described in endometriosis via Gasdermin (GASDM) E pyroptotic pathway." (PMID 40529362, 2025). "It is not clear if cancer pyroptotic cell death results in release of cleaved IL-16, as was proven in the case in endometriosis." (PMID 40529362, 2025). "A recent study in endometriosis demonstrated that IL-16 can be cleaved and released during iron overload induced pyroptotic cell death via non-classical GASDME mediated pathway." (PMID 40529362, 2025). "Few studies have assessed the relationship between IL-16 and pelvic pain, with most studies focusing on patients with endometriosis." (PMID 40508188, 2025). "Elevated IL-16 levels in the peritoneal fluid of women with endometriosis, especially in advanced stages, suggest its role in sustaining inflammatory responses in the peritoneal cavity." (PMID 39408600, 2024). "IL-16 serum distribution in women with endometriosis was significantly higher (p = 0.023) in those with severe pain (23.5[17.1 – 32.0])pg/ml compared to those who had mild pain (16.0 [16.0 – 17.8])pg/ml." (PMID 37170270, 2023). "Abundant IL-16 contributes to local inflammation and abdominal pain in endometriosis." (PMID 40529362, 2025).
endometriosis (continued). "The hypothesis, that there could be alternative mechanisms of IL-16 release is supported by findings of the recent study in endometriosis as pyroptosis could be one of novel pathways of IL-16 secretion." (PMID 40529362, 2025). "Additionally, IL-16 levels have been observed to be higher among women with endometriosis and severe chronic pelvic pain (n = 65) compared to those with endometriosis and mild pain (n = 65)." (PMID 40508188, 2025). "IL-16, also known as lymphocyte chemoattractant factor, is a polypeptide pro-inflammatory cytokine that plays a crucial role in immune and inflammatory responses, including the development of endometriosis." (PMID 39767772, 2024). "The findings suggest that IL-16 in the peritoneal fluid may contribute to the pathogenesis of endometriosis by initiating or maintaining inflammatory responses within the peritoneal cavity." (PMID 39767772, 2024). "Also, the level of IL‐16 is found to be increased in the peritoneal fluid of cases diagnosed with endometriosis." (PMID 39110084, 2024). "Studies on IL-6 and IL-16 in women with endometriosis have been inconsistent." (PMID 37170270, 2023). "Serum IL-16 and IL-16 rs4778889 may be important markers for endometriosis in Nigerian, and by extension, African women." (PMID 37170270, 2023). "By starting or maintaining inflammatory reactions in the peritoneal cavity, IL-16 may also contribute to the pathogenesis of endometriosis." (PMID 37936116, 2023). "Interestingly, PMs from patients with endometriosis also exhibited elevated levels of IL-10 and IL-16." (PMID 35565370, 2022). "Not only IL‐16, but also IL‐8 and Regulated on Activation, Normal T Cell Expressed and Secreted (RANTES or CCL5) are increased in peritoneal fluid of women with endometriosis." (PMID 39110084, 2024). "The trends of increased levels of IL-16, IL-18, IL-1β and IFNγ were seen both in PM and PBMC in endometriosis patients." (PMID 35565370, 2022). "We found a significant induction of IL-16 in PM and IL-18 in PBMC isolated from patients with endometriosis." (PMID 35565370, 2022). "Serum IL-6 and IL-16 concentrations were similar in all the women with endometriosis, regardless of the clinical manifestation." (PMID 37170270, 2023). "IL-16, through the peripheral blood mononuclear cells, stimulates the production of proinflammatory cytokines such as IL-6, IL-1β and TNF-α, which have been demonstrated to play a critical role in the pathogenesis of endometriosis." (PMID 37170270, 2023). "In this study, serum IL-6 and IL-16 concentrations were not significantly different in women with endometriosis compared to those without endometriosis." (PMID 37170270, 2023). "We found elevated levels of HO-1 along with IL-10 and the pro-inflammatory cytokines (IL-1β, IL-16, IFNγ) in PM but not in PBMC from endometriosis patients." (PMID 35565370, 2022).
Sepsis (11 papers, 2020 to 2025). Sepsis is defined as life-threatening organ dysfunction caused by a dysregulated host response to infection. "In models of sepsis or cardiac injury, blockade of IL-16 reduced mortality and improved survival and reduced damage via activation of antioxidant pathways." (PMID 40529362, 2025). "In sepsis, circulating levels of IL-16 are increased, while neutralization of IL-16 with Abs reduced mouse mortality and sepsis induced cardiac injury." (PMID 40529362, 2025). "It was reported that NF-κB is activated with TLR-4 and promotes the level of TNF-α, IL-16, and IL-6 in the tissue of sepsis rats." (PMID 41221897, 2025). "IL-16 expression in septic mice was first measured, and the results showed that both cardiac and serum IL-16 expression levels were increased in mice with sepsis induced by LPS or cecal ligation and puncture (CLP) compared with control mice." (PMID 33628366, 2021). "The results showed that neutralization of IL-16 significantly reversed sepsis-induced oxidative stress imbalance in both the heart and the serum." (PMID 33628366, 2021). "In mice with LPS-induced sepsis, both cardiac and serum IL-16 expression levels were increased, but these increases were reversed by PEG-SOD treatment." (PMID 33628366, 2021). "In this study, we examined the effect of IL-16 on sepsis-induced cardiac injury and dysfunction and focused on oxidative stress to elucidate the possible mechanisms." (PMID 33628366, 2021). "In a subsequent LPS-induced mouse sepsis model, neutralization of IL-16 significantly increased survival, reduced the expression of multiple markers of cardiac injury, and improved cardiac function." (PMID 33628366, 2021). "In this study, the effects of IL-16 on sepsis-induced cardiac injury and dysfunction were examined, and the related mechanisms were detected." (PMID 33628366, 2021). "Neutralization of IL-16 may be a beneficial strategy for the prevention of cardiac injury and dysfunction in sepsis patients." (PMID 33628366, 2021). "Similar trends were found for IL-16 expression in mice with CLP-induced sepsis." (PMID 33628366, 2021). "In this study, we determined whether IL-16 participates in sepsis-induced cardiac injury and dysfunction through the regulation of oxidative stress." (PMID 33628366, 2021). "Compared to the control group, signaling pathways such as ANNEXIN, CCL, and CADM showed enhanced relative information flow in sepsis samples, whereas classical immune-related pathways such as MHC-II, APP, IL16, and CD86 were markedly suppressed." (PMID 41346577, 2025). "Not surprisingly, most of the same pathways from sepsis and septic shock were grouped, including CD22, IL16, MHC-II, and CXCL, indicating these pathways are essential for sepsis response." (PMID 36304125, 2022). "The anti-IL-16 nAb-mediated reductions in Nox and MDA levels and the increases in SOD activity and GSH levels in mice with LPS-induced sepsis were reversed by CPUY192018 treatment." (PMID 33628366, 2021). "We found, for the first time, that both cardiac and serum IL-16 expression levels were elevated in both LPS- and CLP-induced mouse sepsis models." (PMID 33628366, 2021). "However, the role of IL-16 in sepsis and its regulatory effects on oxidative stress are unknown." (PMID 33628366, 2021). "The results showed that an anti-IL-16 neutralizing antibody (nAb) significantly reduced mortality and increased serum lactate dehydrogenase (LDH), creatine kinase myocardial bound (CK-MB), and cardiac troponin T (cTnT) levels while improving cardiac function in mice with LPS-induced sepsis." (PMID 33628366, 2021). "The effects of the anti-IL-16 nAb on survival rates in each group were first analyzed, and the results showed that the anti-IL-16 nAb significantly improved survival rates in mice with LPS-induced sepsis but did not affect survival rates in saline-treated mice." (PMID 33628366, 2021).
autoimmune disease (10 papers, 2013 to 2025). A disorder resulting from loss of function or tissue destruction of an organ or multiple organs, arising from humoral or cellular immune responses of the individual to their own tissue constituents. "IL-16 has been implicated in multiple human conditions including inflammatory, autoimmune diseases, infections and cancers." (PMID 40529362, 2025). "The association with IL16 is of particular interest because IL16 gene codes for interleukin-16, a multifactorial cytokine involved in inflammatory and autoimmune diseases as well as cancer risk." (PMID 28574850, 2017). "Several polymorphisms of IL-16 gene have been associated with cancer and autoimmune diseases." (PMID 40529362, 2025). "Therefore, IL-16 polymorphisms were investigated in several diseases and its association with autoimmune diseases; viral hepatitis B, HBV related HCC and a range of cancers, including prostate, gastric and colorectal cancer has been evaluated." (PMID 29564064, 2018). "Interestingly, pyroptosis is implicated in multiple autoimmune diseases and common triggers of autoimmunity such as immune-complexes, secondary necrotic cell debris, extracellular damaged DNA could possibly trigger pyroptosis, and hypothetical IL-16 release." (PMID 40529362, 2025). "In an animal model of autoimmune disease, CD4+ immune cells, attracted and activated by IL-16, are associated with neuroinflammation." (PMID 38750122, 2024). "Several studies have focused on IL-16 as an immunomodulatory cytokine that takes part in Th1 polarization in autoimmune diseases." (PMID 30936868, 2019). "In another similar study, variation of IL-16 gene recognized as biomarker for facility of Grave’s autoimmune disease diagnosis." (PMID 29564064, 2018). "An increased level of IL-16 mRNA and protein was observed in patients with inflammatory or autoimmune diseases, and the high expression of IL-16 mRNA correlated with increased numbers of CD4+ cells in acute skin lesions." (PMID 24288444, 2013). "IL-16 is a pleiotropic cytokine whose functions include chemoattraction and modulation of T cell activation and is an important mediator in inflammatory and autoimmune diseases as well as in tumor growth and progression." (PMID 25954818, 2015). "IL-16, as a pro-inflammatory cytokine whose functions include chemoattraction and modulation of T cell activation, is an important mediator in inflammatory and autoimmune diseases, as well as in tumor growth and progression." (PMID 25954818, 2015). "Additionally, the increased levels of proteins such as IL16, IL22 and SNCA in male MRL mice upon BaP exposure may be a molecular link to the increased risk in end organ damage in subsets of autoimmune disease patients." (PMID 41155532, 2025).
Crohn disease (10 papers, 2007 to 2024). A gastrointestinal disorder characterized by chronic inflammation involving all layers of the intestinal wall, noncaseating granulomas affecting the intestinal wall and regional lymph nodes, and transmural fibrosis. "Also, -295 T>C polymorphisms in promoter region of IL-16 is associated with increased IL-16 expression which was studied in Crohn’s disease." (PMID 29564064, 2018). "In contrast, patients with Crohn's disease or with Q fever endocarditis had low levels of IL-16 and nucleosomes." (PMID 17551575, 2007). "IL-16 and IL-18 had a suggestive association with an increased risk of ulcerative colitis (UC), and CXCL10 had a suggestive association with an increased risk of Crohn’s disease (CD)." (PMID 37228614, 2023). "Indeed, untreated patients with intestinal manifestations of WD exhibited significantly higher circulating levels of IL-16 than patients with ulcerative colitis (p<0.05) or Crohn's disease (p<0.01)." (PMID 17551575, 2007). "Other notable markers up-regulated selectively in CD submucosa/wall compared to control include IL36a, IL16, and complement C9, while C6 is selectively increased in mucosa, highlighting a potential and perhaps underappreciated role for complement in the pathogenesis of Crohn’s disease." (PMID 38791146, 2024). "IL-16 was elevated in CDI patients than in healthy donors and was also elevated in patients with Crohn’s disease and ulcerative colitis." (PMID 32457246, 2020). "Indeed, circulating levels of IL-16 were not increased in patients with ulcerative colitis or Crohn's disease even though IL-16 is expressed in tissue lesions." (PMID 17551575, 2007).
viral infection (10 papers, 2017 to 2025). "IL-16 is included in a four-biomarker blood signature that discriminates host systemic inflammation caused by a viral infection from other etiologies." (PMID 37628973, 2023). "At least, our in vitro data and mouse infection model provide the insight that IL16 displays a comprehensive functional activity in response to viral infection and prospect IL16 as a potential therapeutic target." (PMID 34630361, 2021). "Since IL16 expression is a biomarker signature to systemic inflammation due to virus infection including IAV, we detected the IL16 level in the serum samples from IAV-infected children." (PMID 34630361, 2021). "Interleukin 16 (IL16) has been known as one of the blood signature biomarkers discriminating systemic inflammation due to viral infection vs. other etiologies." (PMID 34630361, 2021). "IL-16 functions as a modulator of T cell activation and can inhibit HIV replication and it was shown that IL-16 could prevent or delay virus infection of hypothalamus and inhibit virus from spreading into optic nerve and retina." (PMID 28194184, 2017). "Three of the genes (ISG15, OASL, IL16) have previously been reported to be associated with host response to viral infection, although they are not entirely specific to such a response." (PMID 28588308, 2017). "The roles of IL16 in B cells and other virus infection remain largely unknown." (PMID 32735617, 2020). "Interleukin 1 (IL-1) family of cytokines, such as IL-1β and IL-16 are secreted when the NOD-like receptors (NLRs) detect intracellular bacterial and viral infections and induce the inflammasome complex." (PMID 34070595, 2021). "Furthermore, IL-16 depletion enhances the activities of Th1 and CD8+ T cells during virus infection." (PMID 38291041, 2024). "The previous study has identified and validated a peripheral-blood signature to discriminate host systemic inflammation due to viral infection, and the specific signature genes include ISG15, Interleukin 16 (IL16), OASL, and adhesion G protein-coupled receptor E5." (PMID 34630361, 2021).
inflammatory bowel disease (9 papers, 2007 to 2024). A spectrum of small and large bowel inflammatory diseases of unknown etiology. "IL-16 significantly contributes to pathologies associated with inflammation, like inflammatory bowel disease." (PMID 37628973, 2023). "Elevated levels of IL-16 have been reported in patients with inflammatory bowel disease and neonatal sepsis." (PMID 35280991, 2022). "IL-16 has been suggested to play crucial role in several inflammatory diseases by promoting the secretion of cytokines, such as allergic rhinitis, inflammatory bowel disease (IBD)." (PMID 31375554, 2019). "Also, upregulation of IL-16 has been observed in psoriasis, systemic sclerosis, inflammatory bowel disease, and several malignancies." (PMID 33931094, 2021).